NELFB (negative elongation factor complex member B)
Description:
Essential component of the NELF complex, a complex that negatively regulates the elongation of transcription by RNA polymerase II. The NELF complex, which acts via an association with the DSIF complex and causes transcriptional pausing, is counteracted by the P-TEFb kinase complex. May be able to induce chromatin unfolding. Essential for early embryogenesis; plays an important role in maintaining the undifferentiated state of embryonic stem cells (ESCs) by preventing unscheduled expression of developmental genes (By similarity). Plays a key role in establishing the responsiveness of stem cells to developmental cues; facilitates plasticity and cell fate commitment in ESCs by establishing the appropriate expression level of signaling molecules (By similarity). Supports the transcription of genes involved in energy metabolism in cardiomyocytes; facilitates the association of transcription initiation factors with the promoters of the metabolism-related genes (By similarity). (Microbial infection) The NELF complex is involved in HIV-1 latency possibly involving recruitment of PCF11 to paused RNA polymerase II. In vitro, binds weakly to the HIV-1 TAR RNA which is located in the long terminal repeat (LTR) of HIV-1.
Synonyms: NELF-B; COBRA1; KIAA1182
Tractability: Small molecule: a structure with a bound ligand is known. PROTAC: ubiquitination databases record sites on it; its protein half-life has been measured.
Gene: Protein-coding gene on chromosome 9 (137,255,327 to 137,273,542, forward strand). Ensembl gene ENSG00000188986.
Subcellular location: Nucleus
Subcellular location (Human Protein Atlas): Nucleoplasm
Pathways (Reactome):
Disease: Abortive elongation of HIV-1 transcript in the absence of Tat; Formation of HIV elongation complex in the absence of HIV Tat; Formation of HIV-1 elongation complex containing HIV-1 Tat; Formation of the HIV-1 Early Elongation Complex; HIV elongation arrest and recovery; Pausing and recovery of HIV elongation; Pausing and recovery of Tat-mediated HIV elongation; Tat-mediated HIV elongation arrest and recovery; Tat-mediated elongation of the HIV-1 transcript
Gene expression (Transcription): Formation of RNA Pol II elongation complex; Formation of the Early Elongation Complex; RNA Polymerase II Pre-transcription Events; RNA Polymerase II Transcription Elongation
Signal Transduction: NTRK3 as a dependence receptor
Gene Ontology:
Molecular function: protein binding; RNA polymerase inhibitor activity
Biological process: negative regulation of transcription elongation by RNA polymerase II; transcription pausing by RNA polymerase II; cell population proliferation; negative regulation of stem cell differentiation; stem cell differentiation; negative regulation of DNA-templated transcription
Cellular component: cytoplasm; NELF complex; nucleoplasm; nucleus
Genetic constraint (gnomAD): Loss-of-function variants: 35 observed, 57.49 expected, observed/expected ratio (o/e) 0.61, 90% interval 0.46 to 0.81. The synonymous counts are far from expectation, so gnomAD's model fits this gene poorly and the ratio says little. Missense variants: 710 observed, 765.74 expected, observed/expected ratio (o/e) 0.93, 90% interval 0.87 to 0.99. Synonymous variants: 436 observed, 345.87 expected, observed/expected ratio (o/e) 1.26, 90% interval 1.16 to 1.37.
Homologues: Orthologues: chimpanzee NELFB (99% identical), dog NELFB (95% identical), rat Nelfb (95% identical), mouse Nelfb (94% identical), pig NELFB (94% identical), macaque NELFB (92% identical), guinea pig NELFB (89% identical), tropical clawed frog nelfb (74% identical), zebrafish nelfb (71% identical), Drosophila melanogaster NELF-B (48% identical).
Diseases named in the same sentence as NELFB in open-access papers:
NELFB is named in the same sentence as 21 diseases in open-access papers, as found by Europe PMC text mining. Sharing a sentence is not in itself a finding about the gene and the disease. The quoted sentences say what the papers report.
breast carcinoma (8 papers, 2013 to 2023). "NELFB appears to play an important role in other tumors including breast cancer, and its mRNA was found to be increased in breast cancer cell lines." (PMID 31888295, 2019). "To determine whether the same was true for human NELFB, we used CRISPR-Cas9 in human breast cancer cells MDA-MB-231 to disrupt the corresponding C-terminal portion of human NELFB (hNELFB), which is over 90% identical to its mouse counterpart." (PMID 37717699, 2023). "To check whether the genes which showed hypomethylation upon drug treatment were hypo or hypermethylated in breast cancer patients, we checked for the methylation status of the genes and found CARD9 and NELFB to be hypermethylated in breast cancer samples using SMARTapp." (PMID 36474139, 2022). "Furthermore, a lack of NELFB expression in breast carcinoma may serve as a useful indicator for poor prognosis, thus pointing at a beneficial role for NELFB." (PMID 32088792, 2020).
prostate carcinoma (2 papers, 2018 to 2019). A carcinoma that arises from epithelial cells of the prostate gland. "An association of NELFB with prostate cancer and upper gastrointestinal adenocarcinomas, with overexpression of NELFB mRNA in these tumors, has been reported." (PMID 31888295, 2019).
acute myeloid leukemia (1 paper, 2022). Acute myeloid leukemia (AML) is a group of neoplasms arising from precursor cells committed to the myeloid cell-line differentiation. "Interestingly, acute myeloid leukemia (AML) patients with both high NELFA or NELFB expression display low survival rates." (PMID 35409193, 2022).
breast tumor (1 paper, 2022). "The drug treatment reversed the methylation pattern CARD9 and NELFB seen in breast tumor samples." (PMID 36474139, 2022).
cytomegalovirus infection (1 paper, 2023). A herpesvirus infection caused by Cytomegalovirus. "KEGG results showed that NELFB was significantly correlated with the B cell receptor signaling pathway, chemokine signaling pathway, Fc gamma R-mediated phagocytosis, human cytomegalovirus infection, and ribosomes." (PMID 38260098, 2023).
ependymoma (1 paper, 2023). A WHO grade II, slow growing tumor of children and young adults, usually located intraventricularly. "In PFA tumors we observed a physical interaction of NELFB with an ependymoma super enhancer mediated by a PFA-specific DNA loop." (PMID 37085539, 2023). "By CRISPR-Cas9-mediated deletion of this CTCF binding site in a ZFTA cell line, we observe significant increase of NELFB transcription, supporting its role as regulatory insulator active in ZFTA but not in PFA ependymoma tumors." (PMID 37085539, 2023).
glioblastoma (1 paper, 2023). The most malignant astrocytic tumor (WHO grade IV). "NSUN6 controls glioblastoma response to temozolomide (TMZ) through NELFB and RPS6KB2 interaction." (PMID 37934565, 2023).
lymph node metastasis (1 paper, 2019). "Hypermethylation of cg26732804 (HHEX) and cg14397361 (NELFB) was significantly associated with the presence of lymph node metastasis (odds ratio [OR], 7.50; 95% CI, 1.61 to 34.95; p = 0.01 and OR, 5.50; 95% CI, 1.16 to 26.14; p = 0.032, respectively)." (PMID 31888295, 2019).
osteoporosis (1 paper, 2023). A condition of reduced bone mass, with decreased cortical thickness and a decrease in the number and size of the trabeculae of cancellous bone (but normal chemical composition), resulting in increased fracture incidence. "Therefore, NELFB and osteoblasts appear to be associated with osteoporosis via hematopoietic progenitor cells." (PMID 38260098, 2023). "NELFB may affect osteogenic differentiation and bone formation by interfering with TCF1, thus providing a potential new drug target for osteoporosis." (PMID 38260098, 2023).
tumor (8 papers, 2016 to 2023). "NELFB overexpression in both human and mouse T cells significantly enhances antitumor immunity and prolongs the survival of tumor-bearing hosts." (PMID 35444206, 2022). "Here the authors show that, by associating with the key T cell transcription factor TCF1, NELFB is required for eliciting CD8 + T cell memory and anti-tumor immune responses." (PMID 35444206, 2022). "In contrast, Tg cells comprised most of the tumor-infiltrating CD8+ cell population, indicating that NELFB-overexpressing T cells are superior to their WT counterparts." (PMID 35444206, 2022).
cancer (3 papers, 2017 to 2023). A tumor composed of atypical neoplastic, often pleomorphic cells that invade other tissues. "It has been reported that NELFB has a synergistic effect with TCF1 in T cell response to cancer, while a non-coding RNA AK045490 inhibits osteogenic differentiation by down-regulating the expression of TCF1, LEF1 and Runx2." (PMID 38260098, 2023). "NELFB is defined as a common essential gene in the Cancer Dependency Map Project." (PMID 37717699, 2023).
infection (1 paper, 2023). The state of being infected such as from the introduction of a foreign agent such as serum, vaccine, antigenic substance or organism. "Following infection of MEFs with the Cre-expressing virus, we were able to isolate single Nelfb−/− clones expressing ectopic NELFB MTs, including MT183, MT194, MT486, and Δ-C60." (PMID 37717699, 2023).
NELFB also shares sentences with these, for which no sentence is quoted: acral melanoma (1 paper); adenocarcinomas of (1); cardiomyopathy (1); glioma (1); hepatocellular carcinoma (1); melanoma (1); prostate (1); prostate tumors (1); triple-negative breast carcinoma (1).